KIT (KIT proto-oncogene, receptor tyrosine kinase)
Diseases named in the same sentence as KIT in open-access papers (continued):
Sharing a sentence is not in itself a finding about the gene and the disease.
melanoma (continued). "Among the down-regulated genes (FC < 0.5), we found an evident under-expression of the c-KIT proto-oncogene (FC = 0.30), whose activation is often associated with increased cell proliferation, specifically in melanoma." (PMID 23642048, 2013). "More recently the Imatinib inhibitor has been evaluated as a treatment option in melanoma patients presenting c-KIT mutations." (PMID 23515890, 2013). "The discovery of constitutively activating mutations in the BRAF and KIT genes in subsets of melanoma has expanded treatment options to include specific molecularly targeted kinase inhibitors such as vemurafinib and imatinib." (PMID 24220097, 2013). "Somatic missense activating mutations in BRAF have been identified in about 60% of primary melanoma lesions, and KIT mutations in 14% and 18% of acral lentiginous and mucosal melanomas, respectively." (PMID 22281663, 2012). "In recent years, BRAF and KIT have become established therapeutic targets in melanoma patients showing activating mutations in these oncogenes." (PMID 22281663, 2012). "Significant clinical benefits have been achieved using the RAF kinase inhibitor, vemurafenib, to treat melanomas showing BRAF mutations and the receptor protein kinase inhibitor, imatinib, to treat melanomas showing KIT mutations." (PMID 22281663, 2012). "One study of 102 melanomas found mutations or increased copy number of KIT in 28% of primary melanomas arising from chronic sun damaged skin, 36% of acral and 38% of mucosal melanomas." (PMID 25562798, 2012). "While BRAF mutations are significantly less frequent in these melanoma subtypes, activating mutations in the KIT gene are often seen." (PMID 22339359, 2012). "Mutations and/or copy number of KIT were increased in 39% of mucosal, 36% of acral, and 28% of melanomas on chronically sun-damaged skin, but 0% on melanomas of non-chronic sun exposed skin." (PMID 22333219, 2012). "In a phase II study of imatinib for advanced melanoma, a substantial proportion of patients with tumors characterized by mutation or amplification of KIT responded to the drug whereas it had limited activity in a nonselected population of melanoma patients." (PMID 22123319, 2011). "Other reports also support the use of specific kinase inhibitors such as imatinib or dasatinib in melanoma patients with activating KIT mutation." (PMID 20426858, 2010). "In conclusion, this report describes the clinical responses to KIT kinase inhibitors in melanoma patients harbouring diverse KIT mutations and supports the utility of selecting patients for therapy based on the identification of KIT mutations." (PMID 20372153, 2010). "KIT mutations were detected in 21% of mucosal melanomas, 11% of acral melanomas, and 16.7% of melanomas arising in chronically sun-damaged skin as indicated by the presence of solar elastosis." (PMID 20426858, 2010). "Given the high incidence of KIT mutations in mucosal melanoma, we plan to conduct a phase II clinical trial with KIT targeting small molecule in this subset of patients." (PMID 20426858, 2010). "KIT has been identified as a of biological importance in melanoma, and mutations (and/or amplification) appear to be largely confined to acral and mucosal subtypes and those associated with chronic sun damage." (PMID 20372153, 2010). "The therapeutic responses to imatinib in this series mirror the clinical experience of other melanoma patients with similar sensitising KIT mutations." (PMID 20372153, 2010). "Mutations in KIT are more frequent in specific melanoma subtypes, and response to KIT inhibition is likely to depend on the identified mutation." (PMID 20372153, 2010). "Four case reports illustrating significant clinical responses to kinase inhibitors highlight the therapeutic potential of KIT mutation screening in advanced melanoma." (PMID 20372153, 2010).
melanoma (continued). "A potential breakthrough in the management of mucosal melanoma has been recently suggested by the observation of relatively high incidence of KIT mutations in mucosal melanomas." (PMID 20426858, 2010). "Second, the genetic location of KIT mutation has successfully been used to guide selection of the KIT inhibitor in melanoma, echoing the broader experience of the use of KIT mutation subtype to select kinase inhibitor therapies in GIST." (PMID 20372153, 2010). "First, clinical tumour characteristics have successfully been used to identify a subgroup of melanoma patients with a high prevalence of therapeutically relevant KIT mutations." (PMID 20372153, 2010). "This encourages clinical studies with c-KIT blockers in patients with mucosal melanomas and appropriate KIT mutations." (PMID 19018266, 2008). "The other melanoma types, including mucosal melanoma, had a high frequency of mutations of the KIT gene." (PMID 19018266, 2008). "Previous studies have reported that less than 10% of melanoma cases involve KIT mutations." (PMID 41506188, 2026). "Additionally, another phase II clinical trial assessed the efficacy and safety of the PLX3397 inhibitor in advanced acral and mucosal melanomas with receptor tyrosine kinase protein (KIT) mutations." (PMID 40918451, 2025). "KIT mutations are most commonly found in acral and mucosal melanomas." (PMID 40331942, 2025). "Furthermore, advancements in molecular oncology have facilitated the detection of mutations in genes like BRAF, NRAS, and c-KIT in canine melanomas." (PMID 41394861, 2025). "KIT mutations, although less frequent, are typically observed in acral and mucosal melanomas." (PMID 41007741, 2025). "For example, BRAF and NRAS mutations are prevalent in superficial spreading and nodular melanomas, NF1 loss is associated with chronic sun-damaged melanomas, KIT mutations are more common in acral and mucosal disease, and GNAQ/GNA11 mutations characterize uveal melanoma." (PMID 41283484, 2025). "In melanoma, it continues to serve as a valuable therapeutic option for patients with KIT mutations or amplifications, with ongoing research focused on refining patient selection, optimizing combination regimens, and integrating imatinib into evolving immunotherapy and precision oncology frameworks." (PMID 41302945, 2025). "Among these, melanoma is the most aggressive form and includes several uncommon subtypes, such as acral, mucosal, and chronically sun-damaged melanomas, that often contain activating mutations in the KIT gene." (PMID 41301010, 2025). "Melanoma patients with c-KIT mutations are being recruited for a phase II research study to determine whether regorafenib is effective as a second-line treatment (NCT02501551)." (PMID 40429850, 2025). "Approximately 15-20% of acral and mucosal melanomas harbor activating mutations in the KIT gene." (PMID 40861441, 2025). "KIT alterations, including mutations and amplification, are critical in malignant melanoma." (PMID 39744440, 2025). "In contrast to CM, MM has a higher KIT mutation rate, which may improve its response to KIT inhibitors compared to other melanomas." (PMID 41369373, 2025). "However, due to the low incidence of KIT mutation-positive melanomas, imatinib’s use in melanoma therapy is limited." (PMID 40331942, 2025). "It has been reported that activating mutations in BRAF or c-KIT may be present in malignant melanoma, which has important implications for the tumor’s response to anticancer drugs targeting BRAF or c-KIT." (PMID 40641936, 2025). "Instead, a comparative analysis of melanoma cell lines derived from primary tumors or the metastasis of human, canine, and equine species showed comparable mutations in proto-oncogenes BRAF, NRAS, and KIT, which are well-known factors regulating proliferation and apoptosis in human melanoma." (PMID 40563676, 2025). "This suggests that KIT mutations can be a significant marker for targeted therapy in melanoma." (PMID 39200315, 2024).
melanoma (continued). "A mutation encountered more commonly in acral and mucosal melanoma is the KIT mutation and these patients may benefit from the use of KIT inhibitors." (PMID 39741925, 2024). "In some melanoma cases, mutations in KIT have been detected more frequently in the acral, mucosal, and chronically sun-damaged skin, a fact that is in accordance with the places that KIT-mutated melanoma first appears." (PMID 38673496, 2024). "In addition, ipilimumab has been shown to be capable of inducing long-lasting responses and was approved by the FDA for patients with advanced melanoma with c-KIT mutations in first- and second-line treatments." (PMID 38534309, 2024). "In contrast, canine melanomas are mostly oral MMs also harboring KIT mutations." (PMID 38397192, 2024). "Ten patients with NGS proven c-KIT mutated melanoma were identified." (PMID 39207855, 2024). "Similarly, one study found that canine melanomas carrying the mutations in exon 11 of KIT significantly correlated with disease recurrence (p = 0.05)." (PMID 38787171, 2024). "In addition, PRKCD was validated to promote the invasion and migration of colorectal cancer cells, control stress fiber formation in melanoma, participate in the invasion of thyroid cancer, and cause persistent KIT activation in colon cancer." (PMID 38347536, 2024). "Our results endorse further investigations of nilotinib for the treatment of KIT-mutated melanoma." (PMID 38417447, 2024). "KIT mutations are rare in melanoma but can be targeted with therapies like imatinib." (PMID 38534309, 2024). "Thus, more studies are warranted to assess the prognostic potential of KIT mutations in canine GISTs and melanomas." (PMID 38787171, 2024). "In melanoma, the c-KIT mutation is rare, occurring in only approximately 3% of melanomas overall." (PMID 38534309, 2024). "Furthermore, they exhibit a different mutational pattern, with KIT mutations being more prevalent in acral and mucosal melanomas." (PMID 38469235, 2024). "The mutation status of KIT in canine melanomas has had contrasting reports." (PMID 38787171, 2024). "Imatinib, a c-KIT inhibitor, has shown promise in patients with c-KIT-mutated melanoma." (PMID 38399429, 2024). "Metastatic melanomas with KIT mutations respond well to targeted therapy using specific inhibitors." (PMID 39449907, 2024). "As shown in the previous studies, mutations of KIT also occur in melanoma, though less frequently." (PMID 37372988, 2023). "Interestingly, melanoma from this latter patient revealed a well-known KIT mutation (p.Leu576Pro), sensitive to Imatinib." (PMID 36901733, 2023). "In cases of advanced melanoma with KIT mutations, alternative treatment strategies, such as immune checkpoint inhibitors or other targeted therapies may be considered." (PMID 37504268, 2023). "However, when they do occur, the most frequent specific somatic mutations in the c-KIT gene in melanoma include KIT D816V mutation." (PMID 37504268, 2023). "Mutations in the c-KIT gene are uncommon in melanoma, with an incidence of approximately 1–2%." (PMID 37504268, 2023). "While imatinib and, most recent nilotinib may have some activity against other KIT mutations in melanoma, such as L576P or V559D, the D816V mutation is generally regarded as less responsive to these targeted therapies." (PMID 37504268, 2023). "However, in melanoma, the D816V mutation in the KIT gene is much less common and is typically associated with acral or mucosal melanomas." (PMID 37504268, 2023). "Some research revealed that the disease’s early and late stages are both characterized by c-KIT immunoreactivity, but whether mutations occur at the onset of melanoma or during the advanced stage due to mutation accumulation, remains unclear." (PMID 37773078, 2023). "KIT mutations are more frequent in mucosal and acral melanomas." (PMID 37373134, 2023). "The mutations in BRAF V600, NRAS Q61, and c-KIT occur early in melanoma development." (PMID 38003476, 2023).
melanoma (continued). "Mutations in the KIT gene, encoding receptor tyrosine kinase c-KIT, are typically found in acral and mucosal melanomas and may be predicted to activate a PAK1-mediated oncogenic pathway, as was documented in other malignancies." (PMID 37830586, 2023). "Interestingly, almost with similar frequency (<15%) the KIT (KIT proto-oncogene, receptor tyrosine kinase) gene is also mutated in melanoma." (PMID 35628196, 2022). "Furthermore, KIT mutations are positively associated with older age, chronic sun damage, as well as mucosal and acral melanomas." (PMID 35954441, 2022). "The KIT rearranging in melanomas with enlargement of 4q12 showed a significant mutations, but advanced tumour sequencing has proven that they may contribute to only 2 to 5% of cases." (PMID 36551688, 2022). "The phase II Tasigna Efficacy in Advanced Melanoma trial suggested that nilotinib, a KIT-selective tyrosine kinase inhibitor, may be an effective therapy option for individuals with KIT-mutated advanced melanoma." (PMID 36532053, 2022). "Besides gene alterations, immunohistochemical studies have revealed overexpression of c-KIT in some melanoma variants, particularly among ocular melanomas (36-91%)." (PMID 35490363, 2022). "This study suggests that the JAK/STAT pathway may mediate response to nilotinib and indicates a need to further evaluate the potential for use of JAK/STAT inhibitors in combination with KIT inhibitors in the treatment of KIT-mutated melanoma." (PMID 35954441, 2022). "In a trial in which imatinib was used to treat 24 patients with either KIT-mutated or KIT-amplified tumors in mucosal, acral or chronically sun-damaged melanoma, the authors concluded that it was effective in KIT-mutated tumors but not in those where the gene was amplified only." (PMID 35159047, 2022). "c-KIT mutations were found not only in GIST but also in melanoma patients." (PMID 35720122, 2022). "explored the frequency of KIT mutations in various melanoma subtypes, and their results, that KIT mutations were detected in 15.6% of mucosal melanomas, 7.7% of CMs, 1.7% of cutaneous melanomas, and 0% of UMs, was published in Clinical Cancer Research in 2008 and cited for 440 times." (PMID 36059617, 2022). "In summary, our study could provide significant guidance for clinical drug management in GIST or melanoma patients with these mutations in the c-KIT gene." (PMID 35720122, 2022). "The authors demonstrated in vitro that the addition of the hepatocyte growth factor (MET ligand) to the melanoma cell lines with the KIT mutation was able to increase cell viability despite the presence of dasatinib, which was reversed by the addition of crizotinib." (PMID 34831002, 2021). "KIT mutation has been reported from 10% to 21% of mucosal melanomas." (PMID 34571863, 2021). "Previous genetic analyses have uncovered increases in KIT mutations in mucosal melanoma." (PMID 33724703, 2021). "However, single-agent activity of imatinib was reported in melanoma patients whose tumors harboured activating KIT mutations, warranting further investigation in this subset of patients." (PMID 33964953, 2021). "Notably, recurrent KIT mutations (p.S476N, p.G498V, p.L640P, p.D810H, p.V852A) were found in 21% (4/19) of the melanomas of the female genital tract; one sample was found to harbor both p.S476N and p.G498V mutations." (PMID 34102999, 2021). "In addition, a single-arm phase II trial (PIANO; NCT02071940) of pexidartinib in advanced KIT-mutated acral and mucosal melanoma is currently ongoing in the UK." (PMID 33918490, 2021). "Studies have shown that in patients with melanoma, KIT variants could be classified as a rare subtype." (PMID 34582363, 2021). "The standard of care for metastatic melanomas with c-KIT mutations is immunotherapy." (PMID 34831002, 2021). "Currently, it is recommended to test KIT mutations in mucosal, acral or primary unknown melanoma, while it should be considered in cutaneous melanoma with chronic sun damage." (PMID 35008245, 2021).
melanoma (continued). "Additionally, recurrent KRAS and KIT mutations occurred predominantly in polygonal and epithelioid cell types of melanoma in the female genital tract." (PMID 34102999, 2021). "In 2014, a case report expanded the melanoma population that could benefit from imatinib to those with somatic exon 8 KIT mutations." (PMID 33918490, 2021). "Interestingly, the recurrent KRAS and KIT mutations occurred predominantly in polygonal and epithelioid cell subtypes, but rarely in spindle cells, in melanoma of the female genital tract." (PMID 34102999, 2021). "A subset of acral and mucosal melanomas may have KIT mutations, in addition to gene amplifications and structural rearrangements, most frequently of the CCND1 gene and SF3B1." (PMID 34571969, 2021). "In addition to the higher mutation load, the presence of activating mutations contributes to imatinib resistance in c-KIT-mutant melanoma." (PMID 33807778, 2021). "The uncontrolled activation of the MAPK signalling pathway in melanomas may be caused by overexpression or hyperactivation of growth factor receptors such as c-Met, c-KIT, and epidermal growth factor receptor (EGFR)." (PMID 34203771, 2021). "In addition, the authors bring evidence of STAT3 pathway inhibition in nilotinib responders and provide a rationale for future research assessing STAT inhibitors in the treatment of KIT-mutated melanomas." (PMID 33918490, 2021). "Interestingly, all these cases were sun-protected mucosal melanomas with high incidence of these KIT/SF3B1 co-mutations in ~20–40% of anorectal melanomas and ~33% of vulvar or genitourinary melanomas." (PMID 34359736, 2021). "In addition, mutations of c-KIT seem to be more common than copy amplifications in melanomas and most of them occur in the kinase domain or in the juxta-membrane domain." (PMID 34831002, 2021). "However, our pathological results do provide further evidence that links KIT mutations and aggressive melanomas because of the association with the presence of ulceration, vascular invasion and increased Breslow thickness in our patients." (PMID 33648909, 2021). "Interestingly, none of the LMM, the paradigmatic type of chronic sun exposure-associated melanoma, harbored KIT mutation." (PMID 33648909, 2021). "Tumors from 606 melanoma patients with recorded clinical variables were screened for KIT mutations." (PMID 33648909, 2021). "Altogether, these genetic alterations influence clinical decisions for metastatic disease management with BRAF and MEK inhibitor treatment being suitable for patients with BRAF-mutated melanomas, while patients with KIT-mutated melanomas benefit from KIT inhibitors." (PMID 34359736, 2021). "Genetic alterations of KIT gene are known to be one of the major causes of melanoma." (PMID 34889232, 2021). "Furthermore, a diversity of KIT mutations was shown in melanoma, some were sensitive to imatinib, while others were either imatinib-resistant or not studied yet." (PMID 33918490, 2021). "We performed pharmacodynamic studies on patients with KIT-mutated melanoma treated with nilotinib, which suggested that the FGF2 axis may be a mechanism of resistance in this subset of melanoma." (PMID 32344828, 2020). "Detectable ctDNA before complete surgical resection in patients with AJCC stage IIIB/C/D (high-risk stage III) with a BRAF, NRAS, or KIT mutant melanoma is an independent predictor of worse melanoma-specific survival (MSS) in patients receiving no systemic adjuvant therapy." (PMID 33233603, 2020). "This agrees with the experiment in Ba/F3 cells showing that mutations in the activation loop of KIT were resistant to imatinib, suggesting that melanoma patients with this type of mutation should be treated with second generation KIT inhibitors instead of imatinib." (PMID 32344828, 2020). "In this form of melanoma also double mutations of KIT exons occured in one case." (PMID 31848942, 2020).